IL10 (interleukin 10)
Diseases named in the same sentence as IL10 in open-access papers (continued):
Sharing a sentence is not in itself a finding about the gene and the disease.
viral infection (continued). "In contrast, indirubin treatment induced an elevated production of IL-10, a pleiotropic cytokine limiting inflammatory responses, in the lung tissues of stressed mice after virus infection (P < 0.01)." (PMID 29285277, 2017). "IL-10 regulatory mechanisms are therefore essential to control severe inflammatory responses produced by viral infections and can thereby, albeit indirectly, be essential for virus clearance." (PMID 28316998, 2017). "A particular subpopulation of monocytes expressing CD16 selectively expanded in dengue, favoring the terminal differentiation of Bc through the production of IL-10, a cytokine regularly increased in this viral infection." (PMID 27560782, 2016). "Further, IL-10+ T cells move in paths adjacent to areas of virus infection, and neutralization of IL-10 enhances virus spread and shapes the innate immune population located adjacent to these foci." (PMID 26991092, 2016). "Several studies have demonstrated that induction of the regulatory IL-10 by probiotic lactobacilli such as L. rhamnosus plays an important role in controlling inflammatory process upon a viral infection to minimize tissue injury." (PMID 27301272, 2016). "Of note, IL-10 can also function in a feedback loop to limit the activity of effector Th1 cells during chronic virus infection." (PMID 27732671, 2016). "IL-10 in particular is critical for the maintenance of persistent viral infections, and many viral pathogens specifically exploit the IL-10 pathway to help evade host immunity." (PMID 27643611, 2016). "Direct virus infection has been proposed as a requirement for IL-10 production by DC during viral persistence, although the exact relationship is unclear." (PMID 26808628, 2016). "Tr1 cell production of IL-10 is known to limit pathogen control during chronic parasitic and viral infections." (PMID 27732671, 2016). "The extent to which localized IL-10 production by T cells occurs in other acute viral infections in organs more resilient to inflammatory damage is uncertain." (PMID 26991092, 2016). "The presence of either vIL-10 or viral induction of cellular IL-10 facilitate pro-M2 polarization of macrophages and virus-mediated immunosuppression, which in turn benefits viral infection and persistence and dampens immune control of viral infection." (PMID 26213635, 2015). "Many studies with other viruses have indicated that IL-10 initiates T cell inactivation during viral infection and have concluded that this can lead to viral persistence." (PMID 26582423, 2015). "IL-10 is released by cytotoxic T cells to inhibit the action of NK cells during the immune response to viral infection in humans." (PMID 25923079, 2015). "The balance between innate IFNs and IL-10 seems to be a prerequisite for an efficient crosstalk between the innate and adaptive arms of the immune system during viral infections, and it appears to be dysregulated in asthmatic lungs." (PMID 25430775, 2015). "During a virus infection, it is likely that M2 macrophages would secrete higher amounts of the suppressor cytokine IL-10, and less innate IFNs." (PMID 25430775, 2015). "This is in agreement with a mechanisms of viral infection reported in higher mammals whereby IL10 has a role in the inhibition of cytotoxicity." (PMID 26397117, 2015). "While several studies have addressed the role of inhibitory receptors and soluble factors such as PD-1 and IL-10, significantly less work has addressed the role of T cell co-stimulatory molecules during chronic viral infection." (PMID 25590581, 2015). "Murine Bregs have been shown to modulate APC function and inhibit CD4+ T cell proliferation but to our knowledge this is the first time this has been demonstrated for IL-10-competent Bregs during a human viral infection." (PMID 24739950, 2014).
viral infection (continued). "While we believe that regulation by Tregs is strain-dependent, a significant role of local anti-inflammatory cytokines like IL-10 in neuroprotection during acute viral infections of the CNS cannot be ignored." (PMID 25391297, 2014). "Studies over the last decade have identified several characteristics common to multiple persistent viral infections including elevated levels of systemic IL-10 and T cell exhaustion." (PMID 24613988, 2014). "To assess the effects of cell-type specific IL-10 deficiency on T cell effector functions and the resulting decision between chronicity versus clearance of the viral infection, we made use of conditional IL-10 knockout mice." (PMID 24244162, 2013). "Removal of IL-10 resulted in the maintenance of robust effectors T cell response and elimination of viral infection." (PMID 24470873, 2013). "Il-10 has shown to have many immunomodulatory properties and has shown to inhibit antiviral T cell responses in other viral infections such as hepatitis B viral infection and HIV in vitro models." (PMID 24040431, 2013). "Then, our results also support the idea that modulation of respiratory IL-10 during RSV infection is an effective way to improve the outcome of viral disease." (PMID 23947615, 2013). "IL-10 can serve as an immunosuppressive cytokine to negatively regulate innate and adaptive immune responses late in parasitic, bacterial and viral infections, promoting chronic viral infections in some cases by limiting anti-viral immunity." (PMID 23620814, 2013). "While a robust T cell response is a hallmark of many acute infections one hurdle inhibiting the clearance of chronic viral infections is that the immune-suppressive cytokine IL-10 modulates the virus-host balance towards induction of T cell dysfunction." (PMID 24244162, 2013). "IL-10 is released to inhibit the action of antiviral NK cells during the immune response to viral infection." (PMID 23800014, 2013). "We focused on DCs, central components of the immune response against pathogen infection, and found that viral infection potently enhanced GC-induced expression of IL-10 and other glucocorticoid-responsive genes by phosphorylating GR through activation of ERK." (PMID 23667643, 2013). "Elevated levels of IL-10 during chronic viral infections are known to contribute to diminished T cell activity and the failure to control viral infection." (PMID 23785537, 2013). "Upon viral infection, circulating levels of IL-10 increase after ∼24 hours to 20 days in mice to facilitate resolution of inflammation promoted by pro-inflammatory cytokines, which are secreted into circulation immediately (∼3–6 hours) after infection." (PMID 23667643, 2013). "IL-10 is an anti-inflammatory cytokine that suppresses viral infection-induced tissue inflammation by affecting various components of the immune system." (PMID 23667643, 2013). "In contrast, the up regulation of IL-10 in persistent viral infection such as lymphocytic chroriomeningitis virus (LCMV) leads to an impaired T cell response." (PMID 24470873, 2013). "Similar to MARC-145 cells, the virus infection resulted in increased expression of IL-1β, IL-8, IL-10, CCL2 and CXCL10 in PAMs." (PMID 23637938, 2013). "We found that cooperation between DEX and NDV on the IL-10 production started as early as 3 hours after the viral infection in DCs." (PMID 23667643, 2013). "Our findings support the conclusions of recent studies in MCMV infection and other viral infections that demonstrate IL-10 as a key cytokine in limiting immune mediated pathology during viral infection." (PMID 22880122, 2012). "As discussed, mammalian IL-10 is an important regulator of immune responses elicited by a plethora of virus infections." (PMID 23012619, 2012). "It is known that several viral infections induce inhibitory pathways, mainly mediated by IL10 production by immune cells as part of their strategies to escape immune surveillance." (PMID 22768144, 2012).
viral infection (continued). "Viral infection did, however, induce significantly increased IL-10 expression levels in the PBMC of animals with fatal viral-bacterial synergy." (PMID 22435642, 2012). "On the other hand, the increased IL-10 production during persistent viral infection induces T-cell inactivation and results in the prevention of viral clearance." (PMID 22253710, 2012). "Inasmuch as antigen presentation and cellular effector activity during a viral infection are regulated by cytokines, we evaluated the levels of serum IL-2, IL- 4, IL-6, IL-10, TNFα and IFNγ from LSIL patients and normal controls." (PMID 22642942, 2012). "The impact of IL-10 during the early phase of persistent viral infections, in particular for the induction of adaptive immunity, has not yet been extensively evaluated." (PMID 22876184, 2012). "The assumption that there is a link between IL-10 and clearance or failure to clear viral infections after CLA treatment in LP patients needs to be confirmed or refuted." (PMID 23061633, 2012). "IL-10 has been cloned and characterized in several teleosts, and following viral infection it has been shown that IL-10 expression increases markedly in Atlantic salmon." (PMID 22693625, 2012). "In contrast, infection with the human apathogenic TCRV resulted in a strong up-regulation of several of these cytokines (IL-6, TNF-α and IL-10) in a manner that, for IL-6 and IL-10, was dependent on productive virus infection." (PMID 21572983, 2011). "The production of these cytokines was further shown to be mechanistically distinct as both IL-6 and IL-10 production were dependent on productive virus infection while TNF-α production was also induced by UV-inactivated particles." (PMID 21572983, 2011). "Our results indicated that the release of CCL2 and IL-10 from DCs was positively related to viral infection while the production of IFN-α and TNF-α was negatively related to viral replication." (PMID 21269456, 2011). "A role for IL-10 in persistent viral infection has been highlighted recently by studies showing that blockade of the IL-10 receptor is associated with resolution of LCMV infection." (PMID 21187913, 2010). "To dissect the mechanisms underlying how IL-10 signaling facilitates WNV infection, we measured cytokine expression in macrophages from IL-10−/− and wild-type mice upon virus infection in vitro." (PMID 19816558, 2009). "Blockade of IL-10 signaling converts a chronic LCMV infection into a rapidly controlled acute viral infection and prevents functional exhaustion of memory T cells." (PMID 19816558, 2009). "In conclusion, IL-10 signaling plays a negative role in immunity against WNV infection, and blockade of IL-10 signaling by genetic or pharmacologic means helps to control viral infection, suggesting a novel anti-WNV therapeutic strategy." (PMID 19816558, 2009). "The activation of mononuclear system cells occurs due to a hypersecretion of proinflammatory cytokines (IFNγ, TNFα, IL6, IL10, M-CSF), as a consequence of a triggering agent, which is often a viral infection." (PMID 18834507, 2008). "With respect to M2-driven B cell proliferation and IL-10 secretion, we analyzed in primary B cells three M2 mutants which, in the context of virus infection, were severely attenuated in establishment and reactivation from MHV68 latency." (PMID 18389062, 2008). "Increased levels of inhibitory cytokines such as Interleukin 10 (IL-10) have been demonstrated during persistent viral infections in humans." (PMID 17570849, 2007). "The data presented in this paper show that IL-10 assists in generating T cell anergy to a viral infection, and that its role is perhaps most important during T cell priming." (PMID 17570849, 2007). "Studies with peripheral blood leukocytes found that during the early phase of infection with dengue virus, increased IL-10 production induces lasting T cell inactivation and decreases the control of virus infection." (PMID 18000543, 2007).
viral infection (continued). "We next wanted to determine if neutralizing IL-10 would have an effect on the developing T cell response during a chronic viral infection." (PMID 17570849, 2007). "We know that IL-10 and type I interferons play a different role during the host immune responses to viral infections." (PMID 16146571, 2005). "Meanwhile, the mRNA expression of IL-10 increased significantly on day 7, indicating that the viral infection may have induced an anti-inflammatory response." (PMID 41514840, 2026). "Our results align with previous studies showing increased IL-10 production during viral infections." (PMID 41150766, 2025). "Increased IL-10 secretion reflects an enhanced immune response to viral infection." (PMID 41426569, 2025). "Under virus infection conditions, the signal pathway of IL-10 production in T cells remains unclear." (PMID 41156600, 2025). "IL-10 is primarily recognized as an anti-inflammatory cytokine, and while it plays a role in modulating immune responses, its dysregulation can produce adverse effects, notably in the context of viral infections like HIV." (PMID 40310370, 2025). "IL10, a key target in our study, plays a dual role in viral infections." (PMID 40430433, 2025). "Investigating the pathways that regulate IL-10 bioavailability and signaling may unveil new targets for more effective modulation of immune responses in viral infections." (PMID 41156600, 2025). "The role of IL-10 during some viral infections in humans or other mammals." (PMID 41156600, 2025). "Consequently, the CD8+ T cells’ function against viral infection is reduced due to their increased activation threshold by IL-10." (PMID 39066368, 2024). "Thus, inhibition of the IL-10 regulatory pathway can be considered one of the treatment approaches to chronic viral infections such as HIV." (PMID 39066368, 2024). "It was also demonstrated that while SOCS1−/− mice experienced higher levels of TNFα, IL-10, and IL-17 compared to wild-type mice, in the context of viral infections, SOCS1 overexpression could decrease the concentrations of virally induced TNFα." (PMID 39867889, 2024). "Interleukin 10 (IL-10) is a key player in the establishment and persistence of viral infections." (PMID 38790916, 2024). "IL-10 and TGF-β1 are two important immunomodulatory cytokines that may be associated with viral infection and host immunosuppression." (PMID 38962699, 2024). "Moreover, IL-10 contributes to memory CD4+ T cell homeostasis and has been linked to the prolonged persistence of CD4+ T cells in the central nervous system during viral infections." (PMID 39697333, 2024). "The similarities in ocular tissue response to viral infections in these two studies could implicate the viral vector, or its persistence from elevated levels of IL-10, as factors for the subclinical inflammation observed in this study." (PMID 39703903, 2024). "IL-10 is an inhibitory cytokine and a key factor in viral infections." (PMID 36541788, 2023). "IL-10 has been reported to promote NK cell antiviral responses during acute viral infection." (PMID 37490342, 2023). "Conversely, blocking of IL-10 signaling improved the function of exhausted T cells in chronic viral infections and simultaneous blockade of IL-10 and PD-1 pathways resulted in elimination of persistent viral infection." (PMID 37346035, 2023). "IL-10 plays a strong protective role in a viral infection of the lung; thus, it may be a good candidate for virus-induced ARDS treatment." (PMID 36914565, 2023). "It has been reported that serum levels of IL-6 and IL-10 are increased in severe viral infection." (PMID 36406394, 2022). "The aspect that appears critical to whether the IL-27-induced IL-10 response attenuates or augments viral infection is timing." (PMID 35634328, 2022). "IL-10 is an important immunoregulatory cytokine that mediates this balance in the immune response, as it can suppress both innate and adaptive immune responses to viral infections." (PMID 35634328, 2022).
viral infection (continued). "IL-10 is an anti-inflammatory cytokine with immunoregulatory functions in viral infections." (PMID 36106521, 2022). "While IL-10 is critical to protect the host from tissue damage during acute immune responses, it also exhibits a detrimental immunopathogenic effect during acute viral infections by downregulation of MHC-II expression." (PMID 35064122, 2022). "Moreover, IL-10 has a protective role for the lung in viral infections as Influenza and acute respiratory syncytial virus (RSV) infection." (PMID 36148228, 2022). "The role of Bregs in viral infections is primarily through IL-10-mediated immunological effects." (PMID 36326397, 2022). "Specifically, IFN-α2 and IL-10 release were high in single viral infections (online suppl." (PMID 35249041, 2022). "Indeed, IL-10 is a known inducer of the HLA-G expression and has also been described in tumor cells independently of viral infections as inducer of HLA-G expression." (PMID 35237271, 2022). "There are mixed reports as to whether IL-27-induced IL-10 increases or decreases survival following viral infection." (PMID 35634328, 2022). "In summary, both viral infection and IL-23 delivery elevated IL-23R and IL-10 expression, which might prolong the viral persistence of vvDD-IL-23 in the TME and, in turn, lead to more IL-23 expression." (PMID 34093846, 2021). "Furthermore, along SARS-CoV-2 induced viral infection, signal transducer and activator of IL-10 secretion led to overexpression of PD-1 and PD-L1 in monocytes and DCs." (PMID 34163490, 2021). "For instance, IL-10 has been known to introduce anergy T cells during viral infection." (PMID 34046036, 2021). "IL-10 and IL-15 are both vital immune mediators against viral infections, especially IL-10." (PMID 33912464, 2021). "IL-6, a proinflammatory cytokine, is essential for escalating the cell response to control persistent viral infection, and expression of IL-10, an important anti-inflammatory cytokine, is significantly elevated in SFTS patients, especially in patients with fatal disease." (PMID 34484214, 2021). "Thus, during either acute or chronic virus infection, it appears that IL-10 primarily functions to sustain an already established GC response." (PMID 33529242, 2021). "Taken together, engagement of TLR7 post-viral infection may play a role in producing anti-inflammatory cytokines such as IL-10, which could lead to a return to homeostasis by controlling the production of proinflammatory cytokines." (PMID 33331816, 2021). "A system-wide analysis of the immune response to the rVSV-ZEBOV Ebola vaccine suggested negative regulation by inflammatory monocytes; additionally, IL-10 blockade restored antigen-specific T cell–derived IL-2–dependent activation of NK cells in other viral infection models." (PMID 32315287, 2020). "IL-10 is important in viral infection, which may relate to immunosuppression of the hosts by inhibiting the synthesis of proinflammatory cytokines." (PMID 32046249, 2020). "The interactions of the type I interferon- and IL-10-mediated pathways could play an important role in modulating innate immune responses during viral infection." (PMID 32849638, 2020). "Type I interferon (IFN) responses are fundamental in host innate immunity against viruses, whereas the production of IL-10 by macrophages during viral infection has been reported to downregulate type I interferon anti-viral immune responses and hamper virus elimination." (PMID 32849638, 2020). "IL-10 induced by L. rhamnosus CRL1505 administration is able to attenuate the expression of TF in inflammatory macrophages recruited in response to TLR3 activation of viral infection." (PMID 32670091, 2020). "To determine whether NK cell-specific IL-10 ablation can lead to a reduction in the systemic levels of IL-10 during viral infection, we measured the IL-10 levels in the peripheral blood of MCMV-infected mice." (PMID 31803193, 2019).